OR2A14 (olfactory receptor family 2 subfamily A member 14)
Description:
Odorant receptor.
Synonyms: OR2A14P; OR2A6; OST182
Tractability: Antibody: UniProt places it where antibodies can reach, with medium confidence; UniProt predicts a signal peptide or a membrane-spanning region; its Gene Ontology location is reachable by antibodies, with medium confidence.
Gene: Protein-coding gene on chromosome 7 (144,123,176 to 144,131,188, forward strand). Ensembl gene ENSG00000221938.
Subcellular location: Cell membrane
Pathways (Reactome):
Sensory Perception: Expression and translocation of olfactory receptors
Gene Ontology:
Molecular function: olfactory receptor activity; G protein-coupled receptor activity
Biological process: detection of chemical stimulus involved in sensory perception of smell; G protein-coupled receptor signaling pathway
Cellular component: plasma membrane; membrane
Genetic constraint (gnomAD): Loss-of-function variants: 8 observed, 6.71 expected, observed/expected ratio (o/e) 1.19, 90% interval 0.69 to 1.86. That is too few expected variants to judge how well the gene tolerates losing a copy. Missense variants: 390 observed, 392.29 expected, observed/expected ratio (o/e) 0.99, 90% interval 0.91 to 1.08. Synonymous variants: 160 observed, 160.6 expected, observed/expected ratio (o/e) 1, 90% interval 0.88 to 1.14.
Homologues: Orthologues: macaque OR2A14 (92% identical), dog OR2A14 (83% identical), mouse Or2a14 (82% identical), rat Or2a14 (82% identical), guinea pig OR2A14 (79% identical), mouse Or2a54 (79% identical), mouse Or2a56 (79% identical), rabbit OR2A14 (79% identical). Paralogues in human: OR2A5 (79% identical), OR2A2 (77% identical), OR2A12 (74% identical), OR2A1 (73% identical), OR2A42 (73% identical), OR2A25 (61% identical), OR2A7 (61% identical), OR2A4 (60% identical), OR10R2 (43% identical), OR4E2 (43% identical), OR7A10 (43% identical), OR7A5 (43% identical), and 116 more.
Diseases named in the same sentence as OR2A14 in open-access papers:
OR2A14 is named in the same sentence as 2 diseases in open-access papers, as found by Europe PMC text mining. Sharing a sentence is not in itself a finding about the gene and the disease. The quoted sentences say what the papers report.
prostate carcinoma (2 papers, 2018 to 2021). A carcinoma that arises from epithelial cells of the prostate gland. "A retroviral insertional mutagenesis screen for mediators of prostate cancer progression, found lung metastases with vector provirus tagging the OR2A14 gene (3.5 kb downstream of the TSS)." (PMID 33963380, 2021).
cancer (1 paper, 2021). A tumor composed of atypical neoplastic, often pleomorphic cells that invade other tissues. "Our study adds weight to the role of OR2A14 in cancer progression." (PMID 33963380, 2021).